CRP (C-reactive protein)
Diseases named in the same sentence as CRP in open-access papers (continued):
Sharing a sentence is not in itself a finding about the gene and the disease.
infection (continued). "Importantly, persistently elevated CRP beyond post-op day 3–4 was associated with the occurrence of infection and complications." (PMID 41153812, 2025). "Based on these findings, the increased count of neutrophils and the high level of CRP after vaccination might provide infection protection for patients facing a high risk of BJIs." (PMID 40051567, 2025). "The specific calculation formula for predicting the risk of infection with DF by nomogram was Logit(P) = 2.342–0.051*age + 0.012*CRP + 1.386*(Wagner grade = 2) + 2.454*(Wagner grade = 3) + 1.744*(Wagner grade = 4) + 2.325(Wagner grade = 5) + 1.312* (PN = Yes)-1,699* (LEAD = Yes)." (PMID 40604114, 2025). "Regarding infection parameters, we observed a significant association between LS and higher grades of WIfI infection score (HR 1.69, CI 1.20–2.38), WIfI composite scores (HR 1.30, CI 1.04–1.62), and higher value of CRP (HR 1.02, CI 1.01–1.03)." (PMID 40660298, 2025). "Instead, hs-cTn should continue to be interpreted strictly as a marker of myocardial necrosis, while infection risk assessment should rely on inflammatory biomarkers (e.g., CRP and leukocyte count) and standardized surveillance criteria, integrated with clinical and procedural risk factors." (PMID 41008500, 2025). "Higher CRP levels were associated with recurrent infections." (PMID 39858363, 2025). "In order to detect patients at risk of clinically significant infection, it is important to evaluate biochemical indicators of inflammation, such as C-reactive protein (CRP) and procalcitonin (PCT), which can be reliable indicators for diagnosing infection, but only in the general population." (PMID 39685604, 2024). "LDNs, PMN-MDSCs, MDSCs, and CRP were better diagnostic markers of infection than M-MDSCs and PCT." (PMID 38609858, 2024). "Based on the exclusion of active infection at the time of admission, elevated CRP levels may be associated with the tumor." (PMID 38698848, 2024). "Moreover, serum inflammatory markers such as erythrocyte sedimentation rate (ESR) and C-reactive protein (CRP) can remain elevated, even in proven cases of infection eradication; thus, their diagnostic accuracy is limited." (PMID 38610707, 2024). "Although IL-6, procalcitonin, and C-reactive protein are commonly utilized biomarkers for assessing infection and hypothesizing potential causes, they primarily reflect inflammation levels and exhibit limited utility in early detection and predicting outcomes." (PMID 39744123, 2024). "Additionally, when comparing the average levels of analyzed parameters relative to the causative agents of the infection, significant differences were observed across all variables, except for CRP and the absolute value of Ly." (PMID 39403639, 2024). "Furthermore, it has been shown that CRP’s half-life is unaffected by comorbidities, and hence the pathological process underlying CRP synthesis, such as infection, should be the determining factor of its concentration." (PMID 39467995, 2024). "However, there have been attempts to modify the use of CRP POCTs by incorporating the tests into a clinical tool that predicted the risk of severe infections in febrile children presenting to EDs, combining clinical signs and CRP results in one score." (PMID 38504318, 2024). "The preoperative CRP value proves to be valuable in assessing the risk of postoperative infections." (PMID 39063921, 2024). "High CRP could be indicative of an infection that might cause similar physical symptoms and should be ruled out." (PMID 39545229, 2024). "Additionally, CRS, fever, PCT, IL-6, and CRP can serve as diagnostic indicators for infection in patients with fever." (PMID 38956649, 2024). "In moderate endemicity, ferritin concentrations were higher in children with malaria infection at every decile of CRP, suggesting that even infections causing a low level of inflammation – possibly asymptomatic infections – were associated with a ferritin concentration increase." (PMID 39450524, 2024).
infection (continued). "As CRP reflects the presence and severity of infection, elevated CRP levels may be associated with mortality." (PMID 39682646, 2024). "The assessment of CRP levels has been found to contribute substantially to early identification of catheter-associated infections in hemodialysis patients, showing superior sensitivity and specificity compared to conventional infection markers." (PMID 38536779, 2024). "Infections caused by an organism of low virulence, such as propionibacterium, coagulase-negative Staphylococci, and Enterococcus faecalis, had low or normal serum CRP levels." (PMID 39493345, 2024). "In the current study, ESR and CRP values were analyzed preoperatively as a benchmark for infection risk, and we observed that elevated levels of both factors are associated with increased infection risk." (PMID 39063921, 2024). "Second, an increasing number of studies have demonstrated a significant correlation between CRP levels and biomarkers associated with oxidative stress, indicating that inflammation and infection may be potential factors influencing oxidative stress." (PMID 39713782, 2024). "Furthermore, elevated CRP levels have been associated with improved outcomes in previous studies of selected cohorts with severe infections." (PMID 39015209, 2024). "For CRP, schoolchildren diagnosed with elevated CRP concentrations were more likely to have higher concentrations of IL-4, which might be an indicator for inflammation associated with infections." (PMID 37111135, 2023). "CRP is widely used as an infection diagnostic marker in clinical practice." (PMID 38111666, 2023). "In addition, there was an association between elevated circulating RIPK3 and CRP, which are indicators of inflammation and infection." (PMID 37640752, 2023). "Indeed, prior infection has been linked not only to CRP levels but also to reduced cognitive function." (PMID 39081969, 2023). "CRP is an acute phase reactant associated with inflammation related to infection." (PMID 38001923, 2023). "At d 4 pre-infection, the supplementation of the broilers’ diets with Myc improved the birds’ immune-associated parameters via increasing (p < 0.05) the levels of IgG and decreasing CRP values, especially at higher doses." (PMID 37237892, 2023). "This study was aimed at examining if the levels of human β-defensins (hBD1 and hBD2) in patients with inflammation can be used as biomarkers for infection or cancer, as well as to examine their diagnostic impact with regard to other conventional biomarkers of inflammation such as CRP or PCT." (PMID 37296737, 2023). "High values of c-reactive protein may indicate infection and are associated with a poor level of cardiorespiratory fitness." (PMID 37130884, 2023). "According to our findings, the Delta CRP before and after PEG implantation could independently predict following peristomal wound infection and all-cause infection, with the best cut-off value of Delta CRP 3 mg/dl." (PMID 37189057, 2023). "Hematological diseases and oncology, organ dysfunction, decrease of white blood cells, neutrophils, lymphocytes, eosinophils, NLR, hemoglobin and platelets, elevated CRP, aggressive manipulation 2 weeks before infection and MDR were associated with poor prognosis." (PMID 37775747, 2023). "However, CRP level associated with the proportion of infection episodes requiring more than 7 days of hospital care: 32% if CRP level was 100–149 mg/L, 43% if 150–199 mg/L and 60% if 200 mg/L or higher (P < 0.001)." (PMID 37314998, 2023). "ROC analysis of cutoff points associated with AUC≥0.8 has identified relatively similar CRP levels (123 to 190 mg/l) as the optimal cutoff point for balancing sensitivity and specificity in the identification of surgical infection for various gastrointestinal cancers." (PMID 37744382, 2023). "In these two scenarios, CRP and neutrophilia might explain either infection conditions or flare of underlined immunomediated diseases." (PMID 37206973, 2023).
infection (continued). "Additionally, CRP level in plasma has previously been associated with alcohol consumption and increases with tissue infection, necrosis, and chronic inflammatory conditions." (PMID 37889500, 2023). "Moreover, the low pH of infection conditions can cause a significant interaction between ficolin-1 and CRP." (PMID 36825008, 2023). "CRP is a sensitive indicator of inflammation and elevates quickly in Babesia infections, and it is unlikely to be a good measure to distinguish the disease severity caused by infection with the various Babesia parasites." (PMID 38133320, 2023). "Moreover, in severe infections, CRP levels were associated with higher anti-spike IgG antibody titers." (PMID 36975366, 2023). "However, the positive association with CRP was strongest for infection-related death in this population at any level of CRP11." (PMID 37016028, 2023). "), Elevated pre-infected CRP (P = 0.027; OR: 1.104; 95%CI: 1.011–1.204) and low pre-infected platelet (P = 0.041; OR: 0.991; 95%CI: 0.982-1.000) were observed as independent risk factors for infection in N-DLBCL patients." (PMID 37864133, 2023). "Importantly, CRP and most of the other biomarkers showed overall higher values for the Delta infection compared to the other variants." (PMID 37388734, 2023). "In general, a CRP elevation reflects systemic inflammation caused by infection or tumour." (PMID 39516365, 2023). "Indeed, in the present cohort, the mean CRP value reached 28.3 mg/L, but was below 20 mg/L in 53.3% of children with a hand infection caused by K. kingae." (PMID 37630683, 2023). "Delta CRP could predict peristomal infection and all-cause infection within 2 weeks (AUROC 0.712 vs. 0.748; p = 0.039 vs. 0.008)." (PMID 37189057, 2023). "CRP values can serve as an indicator to suggest an underlying severe infection versus mild or self-limiting infections for LRTIs, and, when combined with their clinical assessment, this test can help a clinician decide if an antibiotic prescription will be beneficial for the patient." (PMID 36673130, 2023). "In fact, the presence of post-COVID symptoms has been associated with higher neutrophil count, neutrophil/leucocyte ratio, fibrinogen, and CRP levels three months after the infection; however, this study remarked that the association between these biomarkers was symptom-specific." (PMID 37887751, 2023). "These associations may highlight a difference between chronic inflammation (for example, mediated by factors such as resistin during T2D) and acute inflammation (for example, during an infection), which is strongly associated with high CRP levels." (PMID 37697054, 2023). "An increase in CRP levels may be caused by infection, inflammation, trauma, malignancy, or tissue infarction." (PMID 35887814, 2022). "Consistently, dd-cfDNA levels showed a positive association (r = 0.37, p = 0.0005) with C-reactive protein (CRP) blood levels, as determined by studying dd-cfDNA levels in 104 samples from 28 patients and collected close to CRP measurements during infection episodes." (PMID 35755857, 2022). "Smaller incisions, healing by primary intention, and the use of anti-inflammatory drugs were reported to be the major factors associated with low levels of CRP, while surgery-induced infection/aseptic traumatic inflammation was associated with increased CRP levels." (PMID 35743954, 2022). "We also observed that even though 97% of women had at least two co-occurring infections, CRP was only elevated in 30% using a cut-off of >3 mg/L, and that the complex set of interacting infections and nutrient deficiencies modulated the concentration of CRP." (PMID 36079755, 2022). "Last, given that infection has been associated with liability of SZ, the role of CRP in pathogen defense may contribute to its putative protective properties." (PMID 35385317, 2022).
infection (continued). "Furthermore, a multifactorial logistic regression analysis with P < 0.2 as a filter identified Hydromorphone dosage group, age, biological sex, BMI, WBC count, and CRP as clinically important factors that contribute to infection risk." (PMID 35979059, 2022). "CRP is stimulated due to surgery-induced inflammation or any associated trauma/infection." (PMID 35743954, 2022). "In addition, control of the oral local infection is associated with a reduction in serum inflammatory markers including C-reactive protein (CRP) and interleukin-6 (IL-6)." (PMID 36243707, 2022). "CRP is one of the most distinctive indicators of inflammation, involvement in the inflammatory response in vivo through complement activation and receptor-mediated modalities, exhibiting different levels at different time points of pathogenic infection." (PMID 35795185, 2022). "Nevertheless, our study using three different cohorts suggests a role for the clinical biomarker CRP used under infection or inflammation conditions in monitoring risk in those with specific genetic factors for AD development as well as a role in precision medicine-based drug development." (PMID 36550123, 2022). "We hypothesize that CXCR3 ligands used in combination with standard infection markers (CRP, PCT) would improve the diagnostic algorithm for children with neutropenic fever." (PMID 36670590, 2022). "Thus, the increase is primarily due to the inflammation associated with the infection as supported by a similar increase in the acute phase proteins CRP and IL-6 in this study and related ones." (PMID 35113876, 2022). "A diagnostic gold standard test to determine the infection persistence at reimplantation in fact is still missing: to this end, the synovial leucocyte esterase strip test seems to be a promising intra-operative diagnostic tool, beyond serum CRP and ESR assays." (PMID 35216567, 2022). "CRP is a known maker for inflammation in blood and known to be associated with infection." (PMID 36550392, 2022). "Based on these findings, it could be inferred that the CRP test alone may increase the risk of missing early susceptibility to critical infection or inflammation." (PMID 36555941, 2022). "This study assesses the value of the CXCR3 ligands CXCL9/MIG, CXCL10/IP-10 and CXCL11/I-TAC when used to supplement the standard infection markers C-reactive protein (CRP) and procalcitonin (PCT) in the diagnostic algorithm of neutropenic fever in children with cancer." (PMID 36670590, 2022). "Therefore, we determined that hydromorphone dosage, age, biological sex, BMI, WBC count, and CRP are significant risk factors in developing postoperative infections." (PMID 35979059, 2022). "General practitioners (GPs) are influenced by many factors when managing patients with signs and symptoms of an infection, and the C-reactive protein (CRP) test can be a useful diagnostic tool when determining if an antibiotic treatment is likely to prove beneficial or should be withheld." (PMID 35172735, 2022). "Sensitivity analyses using higher CRP thresholds of ≥5 mg/L and ≥10 mg/L broadly yield the same conclusion, although differences in point estimates of relative risk between infection death and cardiovascular or other death were higher than for the ≥2 mg/L threshold." (PMID 35535512, 2022). "As the model evaluated many haematological variables associated with infection, the effect of CRP may have been reduced in the L1 model." (PMID 36550392, 2022). "Moreover, some Th-2 related infections have been associated with lower CRP in pregnancy and lactation, which likely reflects the weighted balance of Th1 vs Th2 immune responses and the down-regulation of Th-1 induced inflammation by Th2 cytokines." (PMID 36079755, 2022).
infection (continued). "When inflammatory reaction or tissue damage occurs in the organism, CRP levels can rise abruptly within hours or 1–2 days, and its level is positively correlated with the degree of infection in the organism, so it is often used as an early diagnostic indicator of bacterial infection." (PMID 35795229, 2022). "However, the persistent association between elevated CRP and infection death in our “fully adjusted” models suggests that factors beyond frailty and comorbidity are relevant." (PMID 35535512, 2022). "However, in our study CRP greater than 230 mg/L was associated with infection with 83% sensitivity and 71% specificity." (PMID 35991254, 2022). "It is notable that recent data have suggested that clonal hematopoiesis of indeterminate potential, a disorder arising from somatic mutations that promote overrepresentation of proinflammatory myeloid clones (and elevated CRP), is associated with increased risk of diverse infections." (PMID 35535512, 2022). "Importantly, as with any diagnostic tool, PCT and CRP should be used embedded in clinical algorithms adapted to the type of infection and the clinical context and setting." (PMID 34563232, 2021). "While WCC, temperature and CRP levels were shown to be associated with cytokines, we believe clinical infection represent the best aggregate of inflammatory markers and a judgement call of the treating physician, why we used it throughout the manuscript to define systemic inflammation." (PMID 34563211, 2021). "In fact, the level of CRP and D-dimer were associated with the postoperative infection." (PMID 34625082, 2021). "Overall, the risk of infection with normal CRP levels (<10 mg/L) was 21/80 = 0.26." (PMID 33499272, 2021). "The low sensitivity could be explained by the low serum CRP concentration in patients with an infection caused by a low-virulence microorganism capable of forming biofilm." (PMID 33247312, 2021). "IL-6 is a key cytokine that triggers increased liver production of acute-phase proteins (APPs), such as C-reactive protein (CRP) and fibrinogen, causing hypercoagulable disease, which is characterized by thrombotic and embolic phenomena and can predict the severity of infection." (PMID 33946649, 2021). "Of note, the diagnostic accuracy to diagnose infections on ECMO decreased when CRP and WBC were combined—which may be explained by overlaying areas of poor specificity with poor sensitivity." (PMID 35155322, 2021). "The highly elevated CRP levels during infection and inflammation especially in association with hyperinflammation during coronavirus infection, may facilitate the neutralization of bacterial PC impeding attachment and invasion of alveolar epithelial cells." (PMID 34630377, 2021). "CRP level upon admission has been associated with severe infection." (PMID 36168478, 2021). "For a better understanding of the inflammatory response, it would be interesting to know if patients with preoperatively elevated plasma levels of CRP had a clinical infection prior to surgery, and if the cause of death is related to inflammatory complications." (PMID 33920422, 2021). "Point-of-care CRP testing was used by all the GPs as guidance for whether an infection was caused by viruses or bacteria." (PMID 34205866, 2021). "However, using a multiple logistic regression analysis including age and gender as co-factors, the occurrence of postoperative infection was an independent co-factor associated with elevated CRP and PCT levels on POD4." (PMID 32785845, 2021). "In addition, we found statistically significant association between high CRP/alb ratio and postoperative infections." (PMID 33740951, 2021). "The strata with high lipid levels (3rd tertile) and BMI greater than the cut-offs (20, 21, and 22 Kg/m2) showed significantly lower hazard of all-cause and infection-related mortality and lower odds of elevated inflammatory markers, namely CRP > 5 mg/dL, WBC >10 X 103/μL, and NL ratio >4." (PMID 34239907, 2021).